NCF2 (neutrophil cytosolic factor 2)
Description:
Subunit of the phagocyte NADPH oxidase complex that mediates the transfer of electrons from cytosolic NADPH to O2 to produce the superoxide anion (O2(-)). In the activated complex, electrons are first transferred from NADPH to flavin adenine dinucleotide (FAD) and subsequently transferred via two heme molecules to molecular oxygen, producing superoxide through an outer-sphere reaction. Activation of the NADPH oxidase complex is initiated by the assembly of cytosolic subunits of the NADPH oxidase complex with the core NADPH oxidase complex to form a complex at the plasma membrane or phagosomal membrane. This activation process is initiated by phosphorylation dependent binding of the cytosolic NCF1/p47-phox subunit to the C-terminus of CYBA/p22-phox (By similarity).
Synonyms: NCF-2; NOXA2; P67PHOX; P67-PHOX
Tractability: Small molecule: a structure with a bound ligand is known. PROTAC: its protein half-life has been measured.
Gene: Protein-coding gene on chromosome 1 (183,554,461 to 183,593,499, reverse strand). Ensembl gene ENSG00000116701.
Subcellular location: Cytoplasm
Subcellular location (Human Protein Atlas): Cytosol
Pathways (Reactome):
Signal Transduction: RAC1 GTPase cycle; RAC2 GTPase cycle; RAC3 GTPase cycle; RHO GTPases Activate NADPH Oxidases; VEGFA-VEGFR2 Pathway
Immune System: Cross-presentation of particulate exogenous antigens (phagosomes); ROS and RNS production in phagocytes
Cellular responses to stimuli: Detoxification of Reactive Oxygen Species
Gene Ontology:
Molecular function: protein binding; superoxide-generating NADPH oxidase activator activity; electron transfer activity; small GTPase binding; superoxide-generating NAD(P)H oxidase activity
Biological process: superoxide anion generation; cellular defense response; innate immune response; respiratory burst; superoxide metabolic process; phagocytosis
Cellular component: cytosol; membrane; NADPH oxidase complex; phagolysosome; plasma membrane; acrosomal vesicle; cytoplasm
Genetic constraint (gnomAD): Loss-of-function variants: 47 observed, 75 expected, observed/expected ratio (o/e) 0.63, 90% interval 0.5 to 0.8. The upper end of that interval is the gene's LOEUF score, 0.8, which puts it in group 3 of 6, group 1 being the genes least tolerant of losing a copy. Missense variants: 521 observed, 663.58 expected, observed/expected ratio (o/e) 0.79, 90% interval 0.73 to 0.84. Synonymous variants: 202 observed, 247.64 expected, observed/expected ratio (o/e) 0.82, 90% interval 0.73 to 0.92.
Homologues: Orthologues: chimpanzee NCF2 (99% identical), macaque NCF2 (98% identical), pig NCF2 (88% identical), guinea pig NCF2 (87% identical), rat Ncf2 (86% identical), mouse Ncf2 (85% identical), dog NCF2 (83% identical), rabbit NCF2 (76% identical), tropical clawed frog ncf2 (52% identical), zebrafish ncf2 (44% identical). Paralogues in human: NOXA1 (29% identical).
Diseases named in the same sentence as NCF2 in open-access papers:
NCF2 is named in the same sentence as 139 diseases in open-access papers, as found by Europe PMC text mining. Sharing a sentence is not in itself a finding about the gene and the disease. The quoted sentences say what the papers report.
chronic granulomatous disease (43 papers, 2006 to 2025). Chronic granulomatous disease (CGD) is a rare primary immunodeficiency, mainly affecting phagocytes, which is characterized by an increased susceptibility to severe and recurrent bacterial and fungal infections, along with the development of granulomas. "Examples of this scenario include NCF2 associated with chronic granulomatous diseases, and LILR2B (important immune mediator)." (PMID 40208878, 2025). "NCF2 has been proved to play an important role in the microbial phagocytosis, and its mutation can cause chronic granulomatous disease." (PMID 36680322, 2023). "NCF2 deficiency resulted in granulomas, and the NCF2 mutation caused diverse and unusual clinical phenotype of chronic granulomatous disease." (PMID 33553270, 2020). "Ncf2 is a causal gene for chronic granulomatous disease, while mutations in Fermt3 lead to leukocyte adhesion deficiency, type 3." (PMID 25115202, 2014). "In addition, in our recent work on Pstpip2-KO induced autoinflammatory disease, chronic multifocal osteomyelitis, and Ncf2-KO–induced chronic granulomatous disease, we demonstrated that genetic loss of Morrbid mitigated these 2 autoinflammatory diseases too." (PMID 40906528, 2025). "We present two rare cases of p67phox-deficient chronic granulomatous disease (CGD) caused by compound heterozygous mutations in the NCF2 gene." (PMID 39501406, 2024). "Literature reports concerning NCF2 were mostly involved in immune infiltration, oxidative stress, and inflammation-related diseases, such as chronic granulomatous disease, major depressive disorder, and non-alcoholic fatty liver disease." (PMID 39296904, 2024). "Mutations in the five structural genes (NCF1, NCF2, NCF4, CYBA, CYBB) are associated with chronic granulomatous disease (CGD), a condition characterized by impaired production of reactive oxygen species (ROS)." (PMID 37533075, 2023). "NCF2 (neutrophil cytosol factor 2) encodes a subunit of NADPH oxidase, and mutation in this gene can result in chronic granulomatous disease." (PMID 32821283, 2020). "Chronic granulomatous Disease (CGD) is a rare innate immunodeficiency disorder caused by mutations in one of the six genes (CYBA, CYBB, NCF1, NCF2, NCF4, and CYBC1/EROS) encoding the superoxide-producing nicotinamide adenine dinucleotide phosphate (NADPH)—oxidase complex in phagocytes." (PMID 33746979, 2021). "It has been previously shown that patients with hypersensitivity pneumonitis (HP), a rare initial presentation in chronic granulomatous disease (CGD) have mutations in NCF1 and NCF2 genes and are more susceptible to invasive pulmonary A. fumigatus infection." (PMID 37790311, 2023). "Patient P55 was found to have rare exonic variants in both NCF1 (c.269G>A; p.R90H; HGNC:7660) and NCF2 (c.812A>G; p.Lys271Arg; HGNC:7661), which are primarily linked to chronic granulomatous disease (CGD, OMIM 233700)." (PMID 35743704, 2022). "Chronic granulomatous disease is an immunodeficiency disease caused by defects in any of the five structural components of the NOX enzyme, i.e., X-linked recessive mutations in Cybb (gp91phox), or autosomal recessive mutations in Cyba (p22phox), Ncf1 (p47phox), Ncf2 (p67phox), or Ncf4 (p40phox)." (PMID 33842458, 2021). "In particular, Nox2 oxidase function deficiency in phagocytes due to genetic variants (CYBB, CYBA, NCF1, NCF2, and NCF4) has been recognized as a direct cause of chronic granulomatous disease (CGD), an inherited immune disorder." (PMID 29867559, 2018). "Studies of mutations causing human chronic granulomatous disease show that mutations in NCF1, CYBB, CYBA, or NCF2 lead to a complete lack of function of the NOX complex." (PMID 17897462, 2007).
systemic lupus erythematosus (19 papers, 2011 to 2025). An autoimmune multi-organ disease typically associated with vasculopathy and autoantibody production. "Deletion of the PB1 domain would affect the interaction between NCF4 and NCF2, which is an important risk factor for increased systemic lupus erythematosus, a typical systemic autoimmune disease." (PMID 26600390, 2015). "There is evidence that NCF2 can be used as a key gene for AS, which is also associated with a variety of diseases and acts as a negative factor in diseases including cancer, leukaemia, myocardial infarction, systemic lupus erythematosus and so on." (PMID 40045169, 2025). "Neutrophil degranulation was the most significantly enriched pathway in this signature, whereas gene network analysis revealed that the lupus-susceptibility risk loci NCF2, ITGAM, NCF1, RASGRP1 and FCGR2A33–35 were high-degree hub genes, suggesting their central pathogenic role in LN." (PMID 35906002, 2022). "In addition to NCF1, other hypomorphic NOX2 subunits associated with lupus might also contribute to the ROS change in pDCs, of which SNPs in NCF2 were reported by different groups." (PMID 35788118, 2022). "In adults, individuals with hypomorphic mutations in NCF2 (p67phox) and female carriers of CYBB (gp91phox) mutations can develop multi-organ autoimmunity such as systemic lupus erythematosus (SLE)." (PMID 39228435, 2024). "Single nucleotide polymorphisms in NCF2 are associated with diminished NADPH oxidase activity, which in turn is involved in the pathogenesis of systemic lupus erythematosus." (PMID 36177003, 2022). "The importance of NADPH oxidase complex and ROS production in lupus pathogenesis is also supported by the NCF2 locus at 1q25.3 that encodes p67phox, another core component of the multi-protein NADPH oxidase where the lupus risk variant is also associated with decreased ROS production." (PMID 39624492, 2024). "Furthermore, haploinsufficiency of Ncf2 has been demonstrated to be sufficient to accelerate the progression of lupus." (PMID 35788118, 2022). "In addition to CGD, many studies have identified that alterations in the NCF2 gene sequence might be related to the onset of lupus and lupus-like diseases." (PMID 37813633, 2023). "Interestingly, in a lupus mouse model, knockdown of just the p67phox subunit reduces splenic CD8+ T cells suggesting the Ncf2 peptide could be important for also activating CD8+ T cells in other inflammatory diseases." (PMID 38274832, 2023).
diabetes (12 papers, 2010 to 2023). "We applied the Attie Lab Diabetes database to verify the hub gene mRNA levels in obesity, which indicated that expression of TYROBP, TLR8, FCER1 G, HCK, NCF2, CTSS and C3AR1 was significantly up-regulated in 10-week obese mice as compared to the lean group." (PMID 32684073, 2020). "Additionally, other four genes (FCGR1A, NCF2, MYOC, and FABP3) (in bold) were also enriched in these OP- and diabetes-related biological processes and pathways, comparing to the target genes in the TF network." (PMID 36050744, 2022).
atherosclerosis (10 papers, 2020 to 2025). A disease characterized by the build-up of fatty material and calcium deposition in the arterial wall resulting in partial or complete occlusion of the arterial lumen. "Our results provided novel targets for predicting atherosclerotic plaque progression and confirmed that ALOX5 and NCF2 have good diagnostic value for atherosclerosis." (PMID 36035208, 2022). "NCF2 (p67phox) had been identified as potential diagnostic biomarkers in patients with obstructive coronary artery and psoriasis complicated with atherosclerosis." (PMID 36035208, 2022). "Few studies, however, have evaluated the potential mechanism of the correlation between the NCF2 variant and the progression of atherosclerosis." (PMID 33613306, 2021). "Recent studies have discovered that Jak2V617F, ALOX5, and NCF2 are involved in the formation of atherosclerosis by regulating macrophage ferroptosis." (PMID 36290297, 2022). "Our study also found that new genes like CSF2RB, IL1RN, CCL5, MMP9, CD53, NCF2 and TLR2 associated with Inflammation present high expression both in psoriasis and atherosclerosis." (PMID 34122426, 2021). "In addition, VCAM1, NCF2, RAC2, MMP9, and ICAM1 were associated with fluid shear stress and atherosclerosis." (PMID 38640295, 2024). "However, few studies directly analyze the role of NCF2 in psoriasis and atherosclerosis, which emphasizes its importance in future research." (PMID 34122426, 2021). "In this study, we suggested that the progression of atherosclerosis might be related to CD86, C1QB, CD53, C1QC, NCF2, and ITGAM and that it plays a role in regulating immune-competent cells such as T cell CD8 and macrophages M0 and M2." (PMID 32821283, 2020). "However, no research has revealed that NCF2 was involved in atherosclerosis." (PMID 32821283, 2020).
gastric cancer (9 papers, 2019 to 2023). A primary or metastatic malignant neoplasm involving the stomach. "Studies showed that NCF2 might be a potential marker of gastric cancer, and the high expression of NCF2 was associated with the risk of recurrence of renal cell carcinoma." (PMID 35042504, 2022). "For NCF2, early studies specified that NCF2 is overexpressed in gastric cancer and promotes the progression of gastric cancer by activating the NF-kB signaling pathway." (PMID 37775746, 2023). "NCF2 plays a role in inflammation and cancer, e.g., it is highly expressed in gastric cancer promoting tumor metastasis and invasion by activating NF-κB signaling." (PMID 36672328, 2023). "LINC01410 can inhibit miR-532-5p expression, while silencing miR-532-5p reduces inhibition of NCF2, thus upregulating NCF2 expression and activating the NF-κB signaling pathway, exacerbating malignant progression and angiogenesis of gastric cancer." (PMID 37602326, 2023). "Up-regulation of NCF2 promoted gastric cancer metastasis by LINC1410-miR-532-5p-NCF2-NF-κB feedback loop activation." (PMID 33515271, 2021). "A feedback loop consisting of LINC1410/miR-532-5p/NCF2 was also involved in the progression of gastric cancer cells." (PMID 30691465, 2019). "Dysregulation of the miR-532/NCF2-NFkB feedback loop promotes gastric cancer angiogenesis and metastasis, and dysregulation of the miR-126/Crk protein axis predicts poor prognosis in gastric cancer." (PMID 32206186, 2020). "Furthermore, upregulation of NCF2 could promote gastric cancer, angiogenesis, and metastasis." (PMID 34109210, 2021).
Hypertension (9 papers, 2012 to 2023). The presence of chronic increased pressure in the systemic arterial system. "Recent reports demonstrated that NCF2 was significantly associated with hypertension by increasing the expression and activity of NOXs and reactive oxygen species (ROS) generation." (PMID 33613306, 2021). "While the previous studies focused on the role of P67phox or neutrophil cytosolic factor 2 (Ncf2) in the development of hypertension because it is located on chromosome 13, it is important to recognize that both P67phox and P47phox (Ncf1) play a critical role in the activation of ROS in macrophages." (PMID 33377622, 2021). "Increased expressions of Ncf1 and Ncf2 have been described in several models of hypertension." (PMID 24025423, 2013). "As in the case of Eln+/− mice, hypertension of DD mice is related to elevated angII plasma levels, and we have also shown over-expression of several NOX-related genes (Ncf1, Ncf2, Nox2/Cybb and Nox4) and significantly increased oxidative stress in these mice." (PMID 22319452, 2012).
bladder cancer (7 papers, 2015 to 2025). "In bladder cancer, a high expression level of NCF2 was shown to be associated with an undesirable abundance of chemokine CXCL8, a marker of immunosuppressive MDSCs." (PMID 36672328, 2023). "The lncRNA BLACAT3 recruits Y-box binding protein 3 (YBX3) into the nucleus, synergistically increases NCF2 transcription and promotes bladder cancer angiogenesis and blood metastasis by activating the downstream NF-κB signalling pathway." (PMID 40665344, 2025). "LncRNA BLACAT3 was found to have regulatory effects on the expression of NCF2/p67 phox which is clinically correlated with poor prognosis in bladder cancer patients." (PMID 40176927, 2024). "Moreover, increasing the expressions of NCF2, ETFDH, and SON genes are positively correlated with the incidence of death from bladder cancer." (PMID 34589136, 2021).
autoimmune disease (5 papers, 2019 to 2023). A disorder resulting from loss of function or tissue destruction of an organ or multiple organs, arising from humoral or cellular immune responses of the individual to their own tissue constituents. "NCF2, encoding neutrophil cytosolic factor 2, mainly results in autoimmune diseases." (PMID 33553270, 2020). "Apart from NCF1, several single nucleotide polymorphisms (SNPs) in NCF2, NCF4, and CYBA genes were reported to be associated with autoimmune diseases." (PMID 33145364, 2020). "These interesting observations implied that NCF2 gene rs10911363 polymorphism might not be involved in the pathogenesis of autoimmune diseases such as RA and SLE in a Chinese population." (PMID 33145364, 2020). "Recent reports revealed that NCF2 and ITGAM play significant immune-regulatory roles in autoimmune disease." (PMID 32821283, 2020).
glioma (5 papers, 2015 to 2025). A benign or malignant brain and spinal cord tumor that arises from glial cells (astrocytes, oligodendrocytes, ependymal cells). "For example, the redox-associated genes NCF2, VASN, FKBP1B, and TXNDC2 have been identified as central genes, potentially serving as a dependable prognostic indicator for the clinical management of glioma." (PMID 41049606, 2025). "NCF2 encodes a subunit of NADPH oxidase in neutrophils, inhibition of which may suppress glioma progression." (PMID 35111196, 2021).
liver fibrosis (5 papers, 2016 to 2025). "This study suggest that SRF integrates transcriptional activation of NCF1/NCF2 and ROS production to promote liver fibrosis." (PMID 34067715, 2021). "In addition, SRF promotes liver fibrosis by inducing the transcriptional activation of NCF1/NCF2 to promote ROS production." (PMID 40045169, 2025). "Ncf2 gene expression is also upregulated in other liver fibrosis rodent models." (PMID 38274832, 2023). "Two activation domains of the nicotinamide adenine dinucleotide phosphate (NAPDH) oxidase (NOX) complex, NCF1and NCF2, are upregulated during HSC activation augments ROS/RNS production and ultimately liver fibrosis." (PMID 34067715, 2021).
rheumatoid arthritis (5 papers, 2007 to 2020). A chronic, systemic autoimmune disorder characterized by inflammation in the synovial membranes and articular surfaces. "Variations in NCF2, encoding p67phox, and NCF4, encoding p40phox, have been associated with SLE and with rheumatoid arthritis and Crohn's disease, respectively." (PMID 29430280, 2017). "Previous evidence has demonstrated that mutations in NCF1 and NCF2 may cause granulomatous disease, and the copy number variation of NCF1 is associated with rheumatoid arthritis." (PMID 27878450, 2017).